CD4 (CD4 molecule)
Diseases named in the same sentence as CD4 in open-access papers (continued):
Sharing a sentence is not in itself a finding about the gene and the disease.
pemphigus (19 papers, 2016 to 2025). Pemphigus is a group of rare autoimmune diseases that cause blistering of the skin and mucous membranes (mouth, nose, throat, eyes, and genitals).This conditioncan occur at any age, but often strikes people in middle or older age. "Taken together, it is still unclear which subsets of CD4+ T cells play a key pathogenic role in human pemphigus and thus, this area require further study." (PMID 37138879, 2023). "In this model, DSG3-specific CD4+ T cells induce acantholysis, suggesting that DSG3-specific CD4+ T cells contribute to the generation of pathogenic antibodies in pemphigus." (PMID 37138879, 2023). "B cells are the most important cells in induction of pemphigus, but there is growing evidence that autoreactive CD4+ T cells play a pathogenic role." (PMID 37138879, 2023). "In pemphigus vulgaris (PV), the most common clinical variant of pemphigus, several in vitro and in vivo studies demonstrated the critical role of Dsg3-specific CD4+ T cells in the generation of Dsg3-specific auto-ab." (PMID 26872212, 2016). "Higher frequencies of CD19hi B cells existing in SLE and pemphigus patients thus might be due to strong capacity of pathogenic CD4+ T cells to trigger B cell differentiation." (PMID 29066741, 2017). "Since CD4+ T cells help B cells with cognate antigen interaction, it is necessary to investigate the antigen specificity of T cells to evaluate their role in pemphigus." (PMID 37138879, 2023). "To characterize the immune signatures of the inflammatory CD4+ skin infiltrate in LP, BP, and pemphigus patients we collected paraffin-embedded skin biopsies." (PMID 37415985, 2023). "The strong association of certain HLA class II alleles with anti‐Dsg antibody production suggests the involvement of autoreactive CD4+ helper T cells in pemphigus pathogenesis." (PMID 36539957, 2023). "This review describes current views on the role of CD4+ T cells in AIBDs, with a focus on pemphigus and bullous pemphigoid (BP)." (PMID 37138879, 2023). "Many studies have attempted to understand the pathogenicity of CD4+ T cells in pemphigus through use of active mouse models." (PMID 37138879, 2023). "The study demonstrated that skin‐infiltrating CD4+CD69+CCR7− Trm was more prevalent in pemphigus patients than in healthy controls and was positively correlated with the pemphigus disease area index." (PMID 36539957, 2023). "Searching for further evidences about cytokines involvement in DH pathogenesis, we correlated the frequencies of cytokine producing CD4+ T cells from DH patients’ specimens with the clinical score of disease activity Pemphigus Disease Area Index (PDAI)." (PMID 33959126, 2021). "For example, we have reported the presence of both IL-21 and IL-17 in pemphigus lesions, which were secreted by infiltrated CD4+ T follicular helper- (Tfh-) like cells in our previous study." (PMID 34531933, 2021). "Recently, a study reported the over-representation of CD4+ TRM in the lesional skin of patients with pemphigus." (PMID 35187073, 2021). "A deeper analysis of the active pemphigus mouse model revealed that, in these mice, a single Dsg3-specific CD4+ T-cell clone was able to induce a clinical phenotype in recipient mice by activating Dsg3-reactive B cells." (PMID 35187073, 2021). "Other T-cell subsets, including CD4+CD25+ regulatory T cells and Th17 cells, have also been implicated in the pathogenesis of pemphigus." (PMID 34660634, 2021). "Using this analytical approach, we identify modules across microarray datasets obtained from CD4+ T cells in pemphigus and SLE patients." (PMID 29387060, 2017). "Functional blockade antibodies were added when co-culturing fresh CD4+ T with autologous B cells from pemphigus patients." (PMID 29066741, 2017). "Using publically available gene expression data from NCBI GEO database, we investigated gene co-expression networks of CD4+ T cells obtained from pemphigus (PV as well as PF) and SLE patients." (PMID 29387060, 2017).
pemphigus (continued). "Freshly isolated B cells from SLE or pemphigus patients were co-cultured with autologous CD4+ T cells." (PMID 29066741, 2017). "Identification of the “magenta” module suggests common underlying mechanisms for pemphigus and SLE and identifies key regulatory genes for both diseases in CD4+ T cells." (PMID 29387060, 2017). "Microarray data were obtained for peripheral CD4+ T-cell samples from 19 pemphigus patients (4 PV; 15 PF), 13 SLE patients, and 14 healthy controls from NCBI GEO and EBI Array Express (GSE53873; GDS4185)." (PMID 29387060, 2017). "Weighted gene co-expression network analysis (WGCNA) of publicly available microarray datasets of CD4+ T cells was performed, to identify shared gene expression signatures and putative overlapping biological molecular mechanisms between pemphigus and SLE." (PMID 29387060, 2017). "Aim of this study was to investigate cytokines derived from antigen-presenting cells (APC) and their relation to CD4+ T cell subpopulations and to the auto-ab response in pemphigus." (PMID 26872212, 2016). "The aim of this study was to investigate APC-derived cytokines, including IL-27, and their relation to CD4+ T cell subsets and to the auto-ab response in pemphigus." (PMID 26872212, 2016). "Most likely, these cells represent a population of IL-21-positive Tfh cells although in our pemphigus cohort the median percentage of IL-21 single positive T cells is lower compared to the median frequency of CD4+CXCR5+ T cells (16.91% CD4+ T cells)." (PMID 26872212, 2016). "Moreover, FoxP3+CD25hiCD4+ T cells and DSG3-reactive IL-10+CD4+ T cells are reduced in blood from patients with pemphigus compared to healthy individuals." (PMID 37138879, 2023). "In addition to an imbalance in conventional CD4+ T-cell subsets, the amount of circulating regulatory T cells were found to be decreased in patients with pemphigus." (PMID 37138879, 2023). "Evidence of CD4+ T cell involvement in pemphigus pathogenesis has been reported." (PMID 36539957, 2023). "Moreover, expression of CD154 on CD4+ T cells correlated positively with Dsg3 titers in pemphigus patients as shown by Spearman rank correlation (correlation coefficient 0.4634, p= 0.0197)." (PMID 36203615, 2022). "Additionally, serum levels of IL-17 in patients with BP were higher than in control individuals, and the percentage of IL-17-positive cells among CD4+ cells in lesional skin of BP was higher than in that of pemphigus foliaceus." (PMID 32984384, 2020). "Collectively, in this in silico study, we identify novel candidate genetic markers and pathways in CD4+ T cells that are shared between pemphigus and SLE, which in turn may facilitate the identification of novel therapeutic targets in these diseases." (PMID 29387060, 2017). "Of note, IL-21 single positive CD4+ T cells tended to be increased in pemphigus and could be found more frequently (median: 2.36% CD4+ T cells) compared to IL-17/IL-21 double positive CD4+ T cells (median: 0.11% CD4+ T cells) in pemphigus patients." (PMID 26872212, 2016). "Interestingly, in contrast to pemphigus patients IL-10-producing CD4+ T cells were significantly reduced in MG compared to HC." (PMID 26872212, 2016). "However, IL-21-producing Th17 cells only display a minor T cell population in the investigated pemphigus patients (0.11% CD4+ T cells) with IL-21 single positive T cells being more frequent (2.36% CD4+ T cells)." (PMID 26872212, 2016). "So we cannot fully exclude that the increased number of IL-10-producing CD4+ T cells in pemphigus patients may at least partly represent a population of type 1 regulatory T cells that are in transition to Th17 cells as it has been already shown in other inflammatory skin diseases." (PMID 26872212, 2016).
pemphigus (continued). "Circulating (c)Tfh cells (defined as CD4+CXCR5+ T cells) and Th17 cells (IL-17-producing CD4+ T cells) were significantly increased in pemphigus along with increasing IL-21 plasma concentrations suggesting an enhanced activation of IL-21-producing T cells in pemphigus." (PMID 26872212, 2016). "In conclusion, skin TLSs are associated with the maintenance of chronic blister in patients with pemphigus, and the microenvironmental network between clonal CXCL13+CD4+ T cells and Tregs is important for the production of CXCL13 in the TLSs." (PMID 37815865, 2023). "Peripheral CD4+ T cells from SLE and pemphigus patients, which are in an activation status, reinforced the generation of CD19hi B cells after in vitro co-culture." (PMID 29066741, 2017). "To date, alterations in several T cell subsets like CD4+CD25+ Treg and Th17 cells, have been described for pemphigus and MG and are suggested to play a role in the pathogenesis of these diseases." (PMID 26872212, 2016). "Specifically, studies have shown that the lesional skin of pemphigus patients contains substantial numbers of CD4+ T helper cells, CD8+ cytotoxic T cells, and B cells, which are essential for the autoimmune response against desmoglein, the primary antigen in pemphigus." (PMID 40612574, 2025). "Through this study we conclude that skin TLSs are associated with the persistence of chronically recurrent blisters in patients with pemphigus, and the microenvironmental network involving CXCL13+CD4+ T cells and Tregs within these structures plays an important role in CXCL13 production." (PMID 37815865, 2023). "Remarkably, active pemphigus patients exhibited slightly augmented subpopulations of IL-10-producing CD4+ T cells unlike the MG patients who showed reduced percentages of these cells compared to HC." (PMID 26872212, 2016). "To further analyze skin TLSs in pemphigus, we enrolled patients with pemphigus with chronic bullae persisting for more than 4 months, obtained punch biopsies of the chronic lesions, and carried out immunohistochemical studies for CD20, CD138, CD4, and PNAd to identify TLSs." (PMID 37815865, 2023).
prostate tumor (19 papers, 2010 to 2025). "Men with more CD4+ T cells in the prostate tumor environment have an increased risk of dying from PCa." (PMID 36248980, 2022). "The DEG analysis further showed that the expression levels of ZNRD1 in CD4+ T cells were upregulated in prostate tumor tissues versus normal tissues (logFC = 0.51, p = 1.1 × 10−27)." (PMID 41216857, 2025). "CD8+–CD4+ T-cell ratios revealed that untreated prostate tumors contained twice as many CD8+ T cells than CD4+ T cells, while CPG-1668 treatment resulted in more CD4+ T cells, although the cell numbers here were very low." (PMID 38201300, 2024). "The initial evidence that androgen deprivation has immunomodulatory effects came from studies revealing the enhanced infiltration of CD4+ and CD8+ T cells into prostate tumors and changes in CD4+ T cell differentiation following androgen withdrawal." (PMID 36016257, 2022). "Given the complexity of the immune microenvironment and the largely cold characteristics of prostate tumors, even the effective induction of vaccination-specific CD4+ T cells may have been insufficient to tip the balance in favor of a warmer microenvironment." (PMID 40333248, 2025). "Interestingly, cytotoxic TANs isolated from the prostate tumor-bone microenvironment were significantly suppressive of CD4 + T cell proliferation." (PMID 32114681, 2020). "Our previous study has demonstrated that CD4+ T cells in prostate tumor microenvironment contribute to PCa progression; meanwhile, we found increased CD4+ T‐cell infiltration in tumor area after Doc treatment; however, their effects on PCa chemosensitivity remain unclear." (PMID 31018021, 2019). "Various immune cells, namely, CD4+ T cells, CD8+ T cells, natural killer (NK) cells, and macrophages, are enriched in the prostate tumor microenvironment." (PMID 36675580, 2023). "Transglutaminase 4 (TGM4) expression is primarily confined to the luminal epithelia of prostate tumors, and TGM4-pulsed monocyte-derived DCs (moDCs) expanded CD8+ and CD4+ T cells, thus making TGM4 a potential vaccine candidate to treat PCa." (PMID 37738978, 2023). "For example, researchers found that ipilimumab therapy significantly increased VISTA expression on CD4 T cells, CD8 T cells, and CD68+ macrophages from matched pre- and post-treatment prostate tumors." (PMID 36389756, 2022). "Interestingly, Ack1 KO too exhibited activation of CD8+ and CD4+ T cells, compromising ICB-resistant prostate tumor growth." (PMID 38965223, 2024). "However, both the CD4 and CD8 proliferation responses were detected to prostate tumor cell lines, despite the high background responses seen in T cells post vaccination." (PMID 20824184, 2010). "In addition, a recent study in a mouse prostate tumor model found that enzalutamide did not induce immune activation as measured by lack of CD4+ and CD8+ proliferation." (PMID 31013891, 2019).
T-LGL leukemia (19 papers, 2008 to 2025). "Activating STAT5b mutations have also been found in 55% of CD4+/CD8−/TCRαβ+ T-LGL leukemia patients but are very rare among patients with CD4−/CD8+ T-LGL leukemia or NK-LGL." (PMID 38610985, 2024). "On the other hand, somatic mutations in STAT3 gene can also induce constitutive activation of JAK/STAT pathway, as well as mutations on the STAT5b gene, more frequently described in CD4+ T-LGL leukemia." (PMID 34572739, 2021). "STAT3 mutations have been described in 30–40% of T-LGL leukemia patients while STAT5B mutations were found in rare but typical CD4+ T-LGL leukemia cases." (PMID 31963765, 2020). "According to a recent report showing high incidence of STAT5b mutations in CD4+ T-LGL leukemia, we evaluated also the presence of STAT5b mutations in all our cohort of study." (PMID 28977911, 2017). "Notably, CD3+/CD8+/CD57+ LGL leukemia is often associated with autoimmune disorders, while CD3+/CD4+/CD57+ LGL leukemia is associated with monoclonal B lymphocytosis." (PMID 38610985, 2024). "Further data are required to verify whether the CD4+ phenotype of T-LGL leukemia is associated with pSS." (PMID 36362126, 2022). "Moreover, our results provide further evidence of the correlation between STAT5b mutations and CD4+ T-LGL leukemia, recently described in a small cohort of cases (n = 11) and here confirmed in a larger cohort of patients (n = 33) even if with a lower incidence (15.2% vs 55% reported)." (PMID 28977911, 2017). "T-LGL leukemia with the CD8+ CD4− phenotype is due to the development of cytotoxic T lymphocytes that are subject to intense antigenic stimulation and are characterized by disturbances in the mechanism of apoptosis." (PMID 40699662, 2025). "For example, out of 295 patients with T-LGL leukemia, only 5 patients (1.7%) had the CD4+ phenotype." (PMID 36362126, 2022). "Mutations in STAT5B are more frequently associated with T-LGL leukemia, more specifically, CD3+/CD56+ and CD4+ subsets of T-LGL leukemia." (PMID 36755813, 2022). "The majority of T-LGL leukemia involves the TCRαβ+ CD8+ variant (80–90%), while only a small part of the T-LGL leukemia has a TCRαβ+CD4+ (1–5%) or TCRγδ+ phenotype (5%)." (PMID 28407008, 2017). "On the contrary, among CD4+ LGL leukemia patients a high frequency of Vbeta 13.1 was shown (9/29, 31%) as previously reported." (PMID 28977911, 2017). "In fact, STAT3 and STAT5b mutations represent an exclusive marker of CD8+ T-LGL leukemia and CD4+ T-LGL leukemia, respectively." (PMID 28977911, 2017). "From now on we report these two latter subsets together under the definition of CD4+ T-LGL leukemia." (PMID 28977911, 2017). "According to the expression of the NK cell markers CD16, CD56 and CD57, several possible immunophenotype combinations were demonstrated in both CD8+ and CD4+ T-LGL leukemia." (PMID 28977911, 2017). "An increase of CD3+/CD56− or CD3−/CD56+ cells by peripheral-blood flow cytometry and/or an inverted CD4+/CD8+ cell ratio (<1·0) suggests the existence of LGL leukaemia." (PMID 18510682, 2008). "CD4+ T-cell large granular lymphocyte leukemia (T-LGLL) is a rare subtype of T-LGLL with unknown etiology." (PMID 35210405, 2022). "Moreover, out of five patients with pSS-associated T-LGL leukemia, four patients had the typical CD8+ phenotype, and in one patient T-LGLs coexpressed CD4 and CD8." (PMID 36362126, 2022). "Interestingly, our results indicate that CD8+ and CD4+ T-LGL leukemia present different biologic background." (PMID 28977911, 2017). "As indicated, CD16+/CD56- subgroup showed the ANC value significantly lower than that observed in the remaining CD8+ groups and CD4+ T-LGL leukemia patients (mean ANC ± SEM: 795.46 ± 80.03 mm3, 2,855.11 ± 224.54 mm3; 2,635.76 ± 193.81 mm3, respectively, P < 0.05)." (PMID 28977911, 2017). "It has been hypothesized that chronic (antigenic) stimulation would play a major role in the development of the proliferation, as has actually been shown for the TCRαβ+CD4+ T-LGL leukemia type." (PMID 28407008, 2017).